ALB (albumin)
Diseases named in the same sentence as ALB in open-access papers (continued):
Sharing a sentence is not in itself a finding about the gene and the disease.
chronic kidney disease (continued). "CKD: Chronic kidney disease; RAAS: Renin-angiotensin-aldosterone system; BMI: Body mass index; SBP: systolic blood pressure; DBP: diastolic blood pressure; PWV: Pulse wave velocity; ACR: Albumin creatinine ratio; e-GFR: Estimated glomerular filtration rate; U/S: Ultrasound examination." (PMID 37198541, 2023). "The association between albuminuria and epithelial cell apoptosis is established in chronic kidney disease progression, but to date, whether ischemia plays a role, and whether acute/transient albumin exposure is harmful has not been investigated." (PMID 35150207, 2022). "Chronic Kidney Disease (CKD), which is defined as a glomerular filtration rate (GFR) less than 60 ml/min/1.73 m2 or the existence of any renal decline indicators in the urine such as albumin (Liyanageet al., 2022) is a major public health issue worldwide (Hasanet al., 2018)." (PMID 38576797, 2022). "The potential of MSC-Evs in clinical use has been also demonstrated in a previous report, in which administration of MSC-Evs improved symptom, reduced serum creatinine, and improved urinary albumin creatinine ratio without significant side-effects in patients with long-term chronic kidney disease." (PMID 35264186, 2022). "In chronic kidney disease (CKD), the damage to tubulointerstitium may be initiated by reactive oxygen species (ROS) generated due to nephrotoxins such as increased metals and reabsorbed albumin during albuminuria in tubular cells." (PMID 35735634, 2022). "Effects of Sodium-glucose cotransporters 2 (SGLT2) inhibitors on urinary albumin creatinine ratio (UACR) in randomized controlled trials (RCTs) in patients with type 2 diabetes and chronic kidney disease (CKD) of different levels." (PMID 36531469, 2022). "A 62-year-old male patient with a history of renal phosphaturia and slowly progressive chronic kidney disease (CKD) G4A2H presented with fatigue and hypercalcemia (2.7 mmol/L corrected for albumin) with an elevated parathyroid hormone (507 pg/mL)." (PMID 35760966, 2022). "A study showed that patients with chronic kidney disease with lower eGFR levels had higher levels of plasma IL-1 β, IL-1RA, IL-6, TNF-α, hypersensitive CRP, and fibrinogen and that the inflammation score was inverted with GFR estimates and urinary albumin/creatinine ratio (UACR)." (PMID 34992536, 2021). "Chronic kidney disease (CKD) is defined as a reduced glomerular filtration rate (GFR), increased urinary albumin excretion, or both, and has been recognized as an increasing public health issue worldwide." (PMID 34034674, 2021). "Unlike chronic kidney disease, where serum creatinine, urinary albumin-to-creatinine ratio and estimated glomerular filtration rate could be used to identify and as biomarkers for therapeutic efficacy, such biomarkers for NAFLD are less known." (PMID 33643221, 2020). "The response variables were: 1) low glomerular filtration rate (eGFR<60ml/min/1.73m2) estimated by CKD-EPI; 2) increased albumin/creatinine ratio (ACR ≥30mg/g); and 3) chronic kidney disease (CKD)." (PMID 30716076, 2019). "The GNRI was calculated by incorporating serum albumin and anthropometric measurements in 326 patients with nondialysis stage 3–5 CKD who were followed up from September 2011 to March 2017 for end-stage renal disease (ESRD) and the composite outcome of all-cause death and cardiovascular events." (PMID 31739530, 2019). "Another very interesting finding of the current study is that we surprisingly found that mean±SD serum albumin level is only significant in patients on hemodialysis and neither those on peritoneal dialysis nor in chronic kidney disease patients without dialysis therapy." (PMID 29201314, 2017). "Chronic kidney disease (CKD) is defined by the gradual reduction in glomerular filtration rate (GFR) and elevation in urinary albumin excretion." (PMID 27097221, 2016).
chronic kidney disease (continued). "In this group estimated glomerular filtration rate (eGFR) according to MDRD (modification of diet in renal diseases) and CKD-EPI (Chronic Kidney Disease Epidemiology Collaboration) formulas and urine albumin/creatinine ratio (ACR) were determined." (PMID 27575370, 2016). "Chronic kidney disease (CKD) is defined as a reduced glomerular filtration rate (GFR), increased urinary albumin excretion (UAE), or both." (PMID 26697121, 2015). "Various studies demonstrated that ischemia-modified albumin (IMA) is increased in the event of elevated free radical levels such as hypoxia or ischemia-reperfusion that tissues are exposed to sepsis, acute infection, advanced cirrhosis, end-stage renal disease, and advanced cancer." (PMID 24575415, 2014). "The cardiorenal syndrome complicates the treatment of sepsis, as, for example, sepsis-induced hypotension is exacerbated by severe heart failure and edema due to low albumin levels and is further exacerbated by acute kidney injury (AKI) or chronic kidney disease (CKD)." (PMID 39941634, 2025). "Chronic kidney disease (CKD) is currently defined based on a variety of assessed variables indicating abnormalities in kidney structure or function, which include glomerular filtration rate (GFR), urine albumin levels, and the duration of damage." (PMID 41340851, 2025). "Elevated levels of albumin in urine, known as albuminuria, are considered a warning sign of early renal impairment, and the urinary albumin-to-creatinine ratio (UACR) serves as a tool for monitoring the initial stages of chronic kidney disease (CKD)." (PMID 40162309, 2025). "We compared kidney and cardiorenal protection in patients without type 2 diabetes across urine albumin–creatinine ratio (UACR) levels after initiation on dapagliflozin for the treatment of chronic kidney disease (CKD)." (PMID 39165293, 2024). "The occurrence of kidney injury, including acute kidney injury, chronic kidney disease (CKD), and nephritis, is usually realized by reduced glomerular filtration rate (GFR) and the presence of urinary disorders, including urinary albumin excretion and/or hematuria." (PMID 38416371, 2024). "Chronic kidney disease (CKD) is characterized by a consistently diminished estimated glomerular filtration rate (eGFR) of less than 60 mL/min per 1.73 m2 with or without albuminuria (urine albumin to creatinine ratio [UACR] of less than 30 mg/g) for at least three months." (PMID 37566054, 2023). "Additionally, Empagliflozin in the Patients with Chronic Kidney Disease (EMPA-Kidney) trial, empagliflozin was given to those with an eGFR of 20 to 45 mL/min/1.73 m2, or an eGFR of at least 45 to 90 mL mL/min/1.73 m2, and a urinary albumin-to-creatinine ratio of at least 200 mg/gCr." (PMID 37834985, 2023). "Chronic kidney disease (CKD) is defined as significantly impaired kidney function, identified by a reduced glomerular filtration rate (GFR) or increased urinary albumin excretion (albuminuria) that are confirmed on two or more occasions at least 3 months apart." (PMID 35334888, 2022). "Furthermore, the lower the albumin and/or glomerular filtration rate (GFR) levels, the higher the probability of developing chronic kidney disease (CKD)." (PMID 32478016, 2020). "Characteristics of included studies (UAE- urine albumin excretion, GFR-glomerular filtration rate, UPCR-urine protein to creatinine ratio, UACR-urine albumin to creatinine ratio, LYG-life years gained, QALY-quality adjusted life year, CKD-chronic kidney disease)." (PMID 26465773, 2015). "More recently, the DAPA-CKD (Dapagliflozin andPrevention of Adverse Outcomes in Chronic Kidney Disease) trial included 4094patients, irrespective of diabetes status, who presented an eGFR between 25 and75 mL/min/1.73 m2 (CKD-EPI formula) and a urinary albumin-to-creatinineratio ≥200 mg/g." (PMID 39076855, 2023).
chronic kidney disease (continued). "Adults with chronic kidney disease (CKD) with or without type 2 diabetes, with estimated glomerular filtration rate (eGFR) 25 to 75 ml/min per 1.73 m2 and urinary albumin-to-creatinine ratio (UACR) 200 to 5000 mg/g were randomized to dapagliflozin (10 mg once daily) or placebo." (PMID 35497805, 2022). "Univariate analysis revealed nine prognostic factors related to death, i.e., age, malignancy, chronic kidney disease (CKD), coronary artery disease, heart rate >120 beats/min, diagnoses of SJS-TEN overlap and TEN, blood urea nitrogen (BUN) >10 mmol/L, hemoglobin <10 g/dL, and serum albumin <2 g/dL." (PMID 36091688, 2022). "More non-survivors presented with a history of chronic kidney disease; showed symptoms of dyspnea, lung moist rales, and higher BUN; had lower albumin and PaO2 levels; had complications of CMV infection; and received second-line therapy (all P < 0.05)." (PMID 36424963, 2022). "We found that, in the highest PWV group, patients had higher SBP, DBP, glucose, BUN, creatinine, urinary albumin excretion (UAE), uric acid (UA), TC, TG, LDL-C and nonHDL-C levels and higher rates of DM, stroke, HT, CAD, chronic renal failure (CRF)." (PMID 33356026, 2021). "Chronic Kidney Disease (CKD), as defined by the National Institute of Diabetes and Digestive Kidney Disease (NIDDK), is any condition resulting in slow-onset kidney decline, leading to increased urine albumin excretion, decreased glomerular filtration rate (GFR), or both." (PMID 31861598, 2019). "It has been reported that chronic kidney disease (CKD), defined as the sustained presence of a decreased glomerular filtration rate (GFR) with or without increased albumin excretion, has a rather high global prevalence, estimated to be between 11% and 13%." (PMID 29186865, 2017). "Twenty-four patients with stable chronic kidney disease (no fluctuation of GFR > 10% in two months) who presented with edema (pretibial pitting edema from physical examination) and low serum albumin were enrolled in this study." (PMID 22931630, 2012). "In people with chronic kidney disease (CKD), hypoalbuminaemia due to protein losses in the urine, malnutrition or peritoneal dialysis is a common condition, and therefore, glycated albumin and fructosamine may not accurately reflect actual blood glucose." (PMID 40123266, 2025). "In a chronic kidney disease (CKD) rat model, providing a diet rich in ARA and DHA slowed down urinary albumin excretion and reduced levels of plasma lipid peroxides (LPO), indicating that the combination of ARA and DHA could inhibit the progression of early-stage CKD." (PMID 38425758, 2024). "Since albumin is handled by the proximal tubule as a LMW protein, albuminuria per se could be a marker of a dysfunction in the proximal tubule machinery for LMW protein reabsorption which may not constitute a "chronic kidney disease" condition." (PMID 20525263, 2010).
Sepsis (886 papers, 2005 to 2026). Sepsis is defined as life-threatening organ dysfunction caused by a dysregulated host response to infection. "Multivariable logistic regression assessed the RDW-mortality association, adjusted for sepsis, heart failure, coronary artery disease, and albumin." (PMID 42255783, 2026). "Previous research has established that lower serum albumin levels are good predictors of higher risk of death in ICU patients with sepsis and COVID-19, while our work suggests a similar predictive pattern for myocardial infarction patients." (PMID 40739438, 2025). "After further adjusting serum albumin, and blood creatinine based on the Model 2, the relationship between albumin infusion and sepsis risk remains unchanged, with an adjusted OR of 0.37 (95%CI = 0.13–0.88, P = 0.037)." (PMID 40773463, 2025). "One study assessed sepsis as a specific 30-day postoperative outcome, finding low albumin <3.5 g/dL to be associated with increased risk of sepsis in multivariate analysis." (PMID 40103850, 2025). "The reduction of serum albumin is associated with poor outcomes in sepsis patients, which can serve as a predictor of mortality risk in sepsis." (PMID 40978746, 2025). "NT-proBNP, Lactate, Albumin, Oxygenation Index, and Mean Arterial Pressure are independent risk factors for mortality in sepsis patients." (PMID 40470352, 2025). "In this regard, our research fills this research gap, and provides evidence that albumin infusion was likely to decrease the risk of sepsis of AP patients." (PMID 40773463, 2025). "In this study, we found an association between albumin administration and a lower risk of sepsis in AP patients, which persisted after multivariate adjustment." (PMID 40773463, 2025). "Evidence suggests that low serum albumin levels are associated with higher mortality in patients with decompensated cirrhosis and sepsis." (PMID 40636366, 2025). "Univariate Cox regression analysis showed that ALB level on day 7 after ICU admission was associated with the 28-day prognosis of sepsis patients, and the optimal cut-off value was 27.85 g/L." (PMID 40438354, 2025). "We used univariate and multivariate logistic regression models to evaluate the association between albumin infusion and sepsis risk of AP patients." (PMID 40773463, 2025). "Multivariate logistic regression model indicated that albumin infusion was associated with decreased risk of sepsis in the AP patients [adjusted odds ratio (OR)=0.37, 95% confidence interval (CI)=0.13–0.88]." (PMID 40773463, 2025). "We developed and used univariate and multivariate regression models to assess the association between albumin infusion and sepsis risk of AP patients." (PMID 40773463, 2025). "The potential association between albumin-corrected anion gap at admission and prognosis in patients with sepsis-induced AKI remains uncertain." (PMID 40680007, 2025). "High albumin levels (indicated by the blue dots) were associated with a lower sepsis risk, whereas high values of features such as SOFA score, new onset shock, ALB, third-degree burned area, WBC, and inhalation injury indicated a higher risk." (PMID 40901002, 2025). "Further studies are necessary to explore the detailed mechanism of albumin infusion on the risk of sepsis in AP patients." (PMID 40773463, 2025). "Lactate, associated with metabolic acidosis, and albumin, associated with inflammation and vascular permeability, are combined in the L/A ratio and these processes are intimately linked to sepsis and septic shock pathophysiological alterations." (PMID 40283655, 2025). "Hypoalbuminemia in sepsis is caused by increased capillary permeability, increased distribution volume, and a reduced albumin production due to the increased formation of acute-phase proteins." (PMID 40046181, 2025). "The finding indicated that albumin infusion was related to a decreased risk of sepsis after adjusting for confounding variables." (PMID 40773463, 2025).
Sepsis (continued). "The neutrophil-to-PNI ratio emerged as a superior prognostic tool compared to isolated biomarkers such as neutrophil count, absolute lymphocyte count, or albumin, addressing a critical gap in sepsis risk stratification." (PMID 40766844, 2025). "Since sepsis patients often present with renal impairment, the serum albumin level and creatinine level tend to exhibit inverse associations with sepsis prognosis." (PMID 40978746, 2025). "We propose and illustrate a framework for causal inference estimating the effect of albumin on mortality in sepsis using an Intensive Care database (MIMIC-IV) and comparing various sensitivity analyses to results from RCTs as gold-standard." (PMID 39899627, 2025). "Following initial resuscitation in adults with sepsis, hyperoncotic albumin has been associated with improved tissue hypoperfusion compared to 0.9% saline solution." (PMID 39944316, 2025). "Although published study did assess the role of albumin in the prognosis of disease, limited attention has been given to the impact of albumin perfusion on the susceptibility to sepsis in patients with AP." (PMID 40773463, 2025). "In sepsis patients, decreased albumin levels lead to reduced colloid osmotic pressure, causing vascular fluid leakage, tissue edema, and impaired organ function." (PMID 40470352, 2025). "In a 2014 network meta-analysis by Bram, it was found that in sepsis patients, the use of balanced crystalloids or albumin for resuscitation appeared to be associated with reduced mortality compared to other fluids." (PMID 40600034, 2025). "In terms of variable importance, factors such as advanced age, male gender, preoperative sepsis, significant weight loss, hemodialysis, reduced serum albumin levels, and preoperative radiation emerged as key predictors." (PMID 40859558, 2025). "Previous studies have established an association between serum albumin levels at the time of hospital admission in sepsis patients and outcomes such as mortality and renal function." (PMID 39101009, 2024). "The blood urea nitrogen to albumin ratio (BAR) was found to be an independent risk factor for mortality in patients with sepsis (AUR 0.661)." (PMID 38898431, 2024). "The four distinct serum albumin trajectories uncovered in this study highlight the heterogeneity among sepsis patients, suggesting that differing prognoses are associated with varying serum albumin trends." (PMID 39101009, 2024). "Our goal is to uncover the association between the trajectories of serum albumin levels and the occurrence of adverse outcomes among sepsis patients." (PMID 39101009, 2024). "Recent related studies have evidenced that lactateand albumin levels are closely linked to the prognosisof sepsis patients." (PMID 39139159, 2024). "The important risk factors associated with sepsis during hospitalization were the levels of ALB, CRP, and WBC." (PMID 38771840, 2024). "Meanwhile, lactate-to-albumin ratio (LAR) has been confirmed to be associated with mortality rates in conditions such as sepsis, heart failure, and respiratory failure." (PMID 38195421, 2024). "Lower serum albumin levels were associated with increased SOFA scores which means increased severity of sepsis." (PMID 39539863, 2024). "A significant drop in serum albumin after surgery is linked to severe complications, including sepsis, wound infections, and mortality." (PMID 39709362, 2024). "The ACR leveraged early laboratory observations that creatinine levels were positively associated with sepsis, while albumin levels were negatively associated." (PMID 39364026, 2024). "Theresults of this study imply that clinicians should shiftattention towards the lactate/albumin ratio to furtherrefine the risk stratification of sepsis and guide treatmentstrategies." (PMID 39139159, 2024).